AR (androgen receptor)
Diseases named in the same sentence as AR in open-access papers (continued):
Sharing a sentence is not in itself a finding about the gene and the disease.
prostate carcinoma (continued). "Next, RT-PCR was used to examine the expression of the type 1, 2 and 3 AR transcripts in prostate cancer cell lines (VCaP, LNCaP) and normal breast and prostate tissues." (PMID 28035996, 2016). "The androgen receptor (AR) plays an essential role in the establishment and progression of prostate cancer (PCa), and in the metabolic adaptation that takes place during this progression." (PMID 27472325, 2016). "In the case of androgen receptor, amyloid fibers play an important, albeit enigmatic, role in pathologies such as spinal bulbar muscular atrophy and prostate cancer, and should in consequence be considered as potential new therapeutic targets." (PMID 27583469, 2016). "Androgen deprivation therapy, which disrupts AR signaling through androgen ablation or AR antagonists, is the first-line treatment for disseminated prostate cancer." (PMID 27191265, 2016). "In advanced prostate cancer, activation of the AR has a pro-tumorigenic effect, whereas exclusive activation of GR can have an anti-tumorigenic effect." (PMID 27713909, 2016). "The Androgen Receptor (AR) has been the top drug target in prostate cancer for decades, as it plays central roles in the development and progression of such tumors." (PMID 26918604, 2016). "Our studies in human prostate cancer cells also demonstrated inhibitory effects of pterostilbene on AR levels." (PMID 26943043, 2016). "MiR-124 overexpression inhibited the proliferation of prostate cancer cells in vitro and sensitized them to inhibitors of androgen receptor signaling." (PMID 27815936, 2016). "LNCaP cells are classically defined as AR positive, hormone-responsive and metastatic prostate cancer cells." (PMID 27015368, 2016). "Pharmacological inhibition of AR activity by androgen deprivation therapy (ADT) is the mainstay of treatment in prostate cancer, where curative surgery is contraindicated." (PMID 27729622, 2016). "While numerous endogenous AR target genes have been found in prostate cancer derived cell lines, only three have been described in healthy male genital skin fibroblasts." (PMID 27110943, 2016). "Enzalutamide (Xtandi®) is an oral androgen receptor (AR) inhibitor which has been developed for the treatment of prostate cancer (PCa)." (PMID 27486973, 2016). "Accumulating evidence indicates that prostate cancer stem cells lack the androgen receptor and are, indeed, resistant to androgen deprivation therapy." (PMID 26506594, 2016). "Both PSA and AR index (a parameter used to measure the staining intensity of AR) are used as biomarkers for prostate cancer." (PMID 27779102, 2016). "Here, we used high throughput microscopy and quantitative image analysis to evaluate effects of selected endocrine disruptors on AR levels in multiple breast and prostate cancer cell lines." (PMID 26918604, 2016). "To investigate the relationship between PC-1 and AR in prostate cancer progression, we explored the possibility that PC-1 regulates AR protein stability." (PMID 27835608, 2016). "Ectopic KLF4 expression in androgen-independent prostate cancer cells induced AR expression and decreased cell proliferation, invasion and bone metastasis." (PMID 27991915, 2016). "Androgen receptor (AR) expression is most frequently observed in prostate cancer, where it has been shown to promote resistance to radiation." (PMID 27109210, 2016). "Prostate cancer (PCa) that becomes resistant to hormone castration and next-generation androgen receptor (AR)-targeted therapies, called castration-resistant prostate cancer (CRPC), poses a significant clinical challenge." (PMID 27223260, 2016). "Compared to LNCaP prostate cancer cells expressing biologically active levels of the AR, both control fibroblasts and patient samples expressed very low amounts of AR mRNA (≤10% of the LNCaP levels)." (PMID 27609317, 2016). "MAZ was also increased in prostate cancer cells and positively transcriptional regulated androgen receptor." (PMID 27861158, 2016).
prostate carcinoma (continued). "Meanwhile, AIL-induced AR degradation is at least a critical mechanism of AIL-dependent cell growth inhibition in prostate cancer." (PMID 27959342, 2016). "Further studies on the mechanism of DNAH8-mediated AR activity will be required to elucidate the role DNAH8 plays in promoting ligand-independent AR activation in prostate cancer." (PMID 27363033, 2016). "Androgen receptor (AR) signaling is indispensable for the development of castration resistant prostate cancer, and H2S was shown to inhibit AR transactivation and contributes to antiandrogen-resistant status." (PMID 27019751, 2016). "Using prostate cancer cell models, we investigated the regulation and crosstalk between AR and DNAH8." (PMID 27363033, 2016). "For example, loss of PTEN in prostate cancer led to hyper-activation of AKT, which induced AR phosphorylation and androgen-independent activation." (PMID 27363033, 2016). "Androgen receptor (AR) is a male sex steroid-activated transcription factor (TF) that plays a critical role in prostate cancers, including castration-resistant prostate cancers (CRPC) that typically express amplified levels of the AR." (PMID 27641228, 2016). "TQ significantly inhibited androgen-responsive prostate cancer cell proliferation, AR activity, and AR protein expression." (PMID 26986969, 2016). "We thank the numerous colleagues involved in prostate cancer and AR signaling research for many helpful discussions and support, and Dr. H.-F." (PMID 26760770, 2016). "In the present study, we found that the migration and invasion of prostate cancer cells were suppressed by androgen-AR signaling while increased by enzalutamide, an inhibitor of AR, which is consistent with previous reports." (PMID 27191265, 2016). "One major candidate is the androgen receptor (AR), which has been shown to upregulate Fgf8 mRNA in 60–70% of newly diagnosed prostate cancers." (PMID 27200347, 2016). "In particular, the p65/p50 subunit of NF-κB, as a complex with tissue transglutaminase, is able to bind to the AR promoter at NF-κB response element sites in prostate cancer cells." (PMID 27322140, 2016). "Consistent with a role for fatty acid metabolism in sustaining AR levels in prostate cancer in vivo, AR mRNA levels in human prostate tumors correlate positively with expression of ACLY and other fatty acid synthesis genes." (PMID 27248322, 2016). "So far, we have established an inhibitor dose that displayed a clear decrease in the expression of an important cell cycle regulator, CDK1, and a decrease in the expression of AR, a major drug target in prostate cancer." (PMID 26824323, 2016). "Previous reports have suggested that activation of androgen/AR signaling has a positive effect on the initiation and progression of various cancer cells, including prostate cancer, renal cell carcinoma, bladder cancer, and hepatocellular carcinoma." (PMID 27144435, 2016). "It has been established that AR transactivation of target genes in cultured prostate cancer cells requires pioneer factors, such as FoxA1 and GATA2." (PMID 27374105, 2016). "Another H2S-releasing donor, SFN, also suppressed the expression of AR protein by inhibiting the cytoplasmic protein deacetylase HDAC6 in prostate cancer cells." (PMID 27019751, 2016). "TMEFF2 is a previously identified AR-target gene, which has been shown to exhibit anti-proliferative effects in prostate cancer cells." (PMID 27036029, 2016). "An inverse relationship has been observed between androgen receptor (AR) activity and SRC signaling in advanced prostate cancer (PCa); however, the modulation of AR/SRC crosstalk that leads to metastatic PCa is unclear." (PMID 27028864, 2016). "Despite recent improvements in patient outcomes using newer androgen receptor (AR) pathway inhibitors, treatment resistance in castrate resistant prostate cancer (CRPC) continues to remain a clinical problem." (PMID 27046225, 2016).
prostate carcinoma (continued). "Both the AKT and MEK signaling pathways become activated as prostate cancer develops resistance to AR-targeted therapies." (PMID 27046225, 2016). "The promoting role of androgen signaling through the AR in stimulating prostatic tumor cell growth has been well studied in human prostate cancer." (PMID 26862755, 2016). "Androgen receptor (AR) and Mechanistic Target of Rapamycin Complex-1 (mTORC1) activities are two key drivers of prostate cancer." (PMID 27557496, 2016). "Inhibition of androgen receptor (AR) signalling represents the conventional medical management of prostate cancer." (PMID 27729622, 2016). "The SGK3 gene has been reported to be an oestrogen or androgen receptor transcriptional target in ER‐positive breast cancer cells and in androgen receptor (AR)‐positive prostate cancer." (PMID 27481935, 2016). "AR over-activation at high concentration of androgen has been reported to inhibit prostate cancer cell growth." (PMID 27835608, 2016). "The progression from low-grade to high-grade prostate carcinoma and metastases is mediated by down-regulation of the androgen receptor target genes, including DHCR24 (24-Dehydrocholesterol Reductase)." (PMID 27206673, 2016). "This is in keeping with a prior report that suggests that suppression of ligand-dependent AR signaling is a critical contributor to the anti-tumor activity of JQ-1 in prostate cancer cells." (PMID 27276681, 2016). "Altogether, our data suggest the existence of a HIF/PHF8/AR axis that promotes prostate cancer progression and allows us to propose a working model." (PMID 27991916, 2016). "We report that the antibiotic salinomycin, a cancer stem cell blocker, is a dual-acting AR and mTORC1 inhibitor, inhibiting PTEN-deficient castration-sensitive and castration-resistant prostate cancer in culture and xenograft tumors." (PMID 27557496, 2016). "Many AR target genes have been described in prostate cancer-derived cell lines; however, only a handful of genes have been identified in healthy male genital tissue." (PMID 27583472, 2016). "Androgen receptor signaling is crucial for prostate cancer initiation, progression, and development of resistance to antiandrogen therapy." (PMID 27200299, 2016). "We applied genome-wide model-based motif searches to different prostate cancer models and investigated ARE occurrence dependent on AR-splice variants and steroid regulation." (PMID 27623747, 2016). "The AR is recognized as a major contributor to all stages of prostate cancer from carcinogenesis to castration-resistant disease." (PMID 26986969, 2016). "Understanding the physiological functions of downstream molecules of AR is crucial for the development of effective therapeutic strategies targeting prostate cancer." (PMID 27853318, 2016). "In this article we highlighted the existence of multimodal AR kinetics in prostate cancer using a model system." (PMID 26936218, 2016). "As a licensing factor, AR must be degraded during mitosis in order to allow DNA replication to reinitiate for subsequent cell cycling, with AR stabilization during mitosis inhibiting prostate cancer proliferation." (PMID 27835608, 2016). "Although androgen/androgen receptor (AR) signaling promotes prostate cancer progression, suppression of AR signaling induces chemokine (CC motif) ligand 2 (CCL2), which enables prostate cancer cells to gain metastatic potential." (PMID 26701731, 2016). "Prostate cancer remains a deadly disease especially when patients become resistant to drugs that target the Androgen Receptor (AR) ligand binding domain." (PMID 26918604, 2016). "Androgen receptor (AR) targeting remains the gold standard treatment for advanced prostate cancer (PCa); however, treatment resistance remains a major clinical problem." (PMID 27598125, 2016). "The multiple molecular mechanisms by which the androgen receptor (AR) contributes to disease progression despite castration levels of androgens in prostate cancer have been thoroughly reviewed." (PMID 26646591, 2016).
prostate carcinoma (continued). "Because TQ had pronounced inhibitory effect on markers of AR activity, the AR in androgen-sensitive prostate cancer cell lines was examined." (PMID 26986969, 2016). "Zhao and Feldman (2001) found that calcitriol enhanced AR transcriptional activity in androgen-sensitive LNCaP prostate cancer." (PMID 27973439, 2016). "To date, multiple mechanisms are known to elicit aberrant AR activity and thereby facilitate the proliferation and survival of castration-resistant prostate cancers in the context of castration levels of androgens." (PMID 27365400, 2016). "There is substantial prior evidence that fatty acid metabolism is upregulated in prostate cancer and is regulated by the AR." (PMID 27248322, 2016). "The fact that AR silencing has a similar effect strongly suggests that Nutlin-3 does indeed impact on pro-survival AR signalling in human prostate cancer cells." (PMID 27729622, 2016). "In contrast to the oncogenic activity of AR in prostate cancer, AR signaling normally serves to restrain proliferation and stimulate differentiation and survival of luminal prostate epithelial cells in a healthy prostate gland." (PMID 27203692, 2016). "The success of new agents that target the AR means that the AR signaling pathway remains an important driver of prostate cancer in the castration-resistant state." (PMID 27756383, 2016). "Prostate cancers are generally treated by blocking AR activity using some form of androgen ablation therapy that targets the AR ligand binding domain (LBD); this approach has been shown to be therapeutically very effective, at least initially." (PMID 26918604, 2016). "It is well documented that most prostate cancer cells express AR, and they are somewhat dependent on AR signaling for growth and proliferation." (PMID 27203692, 2016). "Androgen signalling through the androgen receptor (AR) is essential for human prostate growth and function; however, excessive AR-signalling activity in the prostate is well-known to be involved in prostate cancer development and progression." (PMID 28035996, 2016). "We refined AR-binding and AREs in AR-positive but androgen-insensitive CWR22Rv1 prostate cancer cells using ChIP-Seq and motif-guided genome-wide analysis." (PMID 27623747, 2016). "Tremendous studies have proven that androgen, which works by binding and activating androgen receptor (AR), is critical for progression of prostate cancer." (PMID 27438705, 2016). "Although AT did not exhibit anti-androgenic properties within our system, vitamin E (VE) analogs have been reported to affect AR protein expression in prostate cancer cells." (PMID 26986969, 2016). "To examine if DNAH8 expression coincides with AR activity in prostate cancer patients, we took a meta-analysis approach and examined the mRNA expression patterns of DNAH8 and PSA as a surrogate for active AR signaling." (PMID 27363033, 2016). "Compared to AT, TQ was found to have distinctive properties on androgen-responsive prostate cancer cell lines with notable actions on the expression of the AR." (PMID 26986969, 2016). "The AR has been shown to be critical to proliferation and survival of the bulk population of prostate cancer cells both in early prostate cancer and in CRPC, but different mechanisms are at play." (PMID 27378372, 2016). "Numerous lines of evidence implicate the androgen receptor (AR) in all stages of prostate cancer, the most common male malignancy." (PMID 27729622, 2016). "The AR is critical for proliferation and survival of the bulk population of prostate cancer cells both at early stages and during CRPC as reflected by the effect of AR-inhibiting therapy." (PMID 27378372, 2016). "The presence of the enzalutamide-agonistic F876L mutation and the presence of dominant AR splice variants limited our ability to test for the efficacy of combined AKT and MEK inhibition together with AR inhibition in advanced prostate cancer models." (PMID 27046225, 2016).
prostate carcinoma (continued). "Several groups have detected F877L mutations (alternatively described as F876L based on older genomic builds) in the AR LBD following chronic treatment of prostate cancer cell lines with enzalutamide or other second-generation anti-androgens such as ARN-509." (PMID 27276681, 2016). "For example, decreased AR expression was achieved in LNCaP human prostate cancer cells using siRNA resulting in a decrease in LNCaP growth." (PMID 26986969, 2016). "Treatment of prostate cancer cells with AR agonist resulted in the inhibition of hTERT promoter activity and, conversely, treatment of AR antagonist failed to recapitulate this inhibition." (PMID 27548225, 2016). "We showed that cytoplasmic REIC/DKK-3 interferes with the dimerization of SGTA and abolishes the function of SGTA as a negative regulator of the AR, resulting in enhanced AR sensitivity in human prostate cancer cells." (PMID 26658102, 2016). "Collectively, these findings suggest that LA exerts the anticancer effect by inhibiting AR and is a valuable therapeutic agent in prostate cancer treatment." (PMID 27399684, 2016). "To date, most interventions against prostate cancer reduce AR activation through inhibiting the production of androgenic ligands, such as testosterone or dihydrotestosterone." (PMID 26986969, 2016). "In summary, salinomycin is the first example of a dual-acting AR/mTORC1 inhibitor, which can inhibit castration-sensitive and castration-resistant human prostate cancer cells in vitro and in xenograft models." (PMID 27557496, 2016). "The current clinical paradigm for the treatment of prostate cancer, even in the castration-resistant state, remains focused on the blockade of AR signalling." (PMID 27036029, 2016). "In conclusion, we demonstrated that AIbZIP is upregulated by SPDEF acting downstream of AR in prostate cancer cells." (PMID 27853318, 2016). "TBLR1 is also a strong coactivator of AR in prostate cancer, leading to selective activation of growth suppressive AR target genes and tumor suppression." (PMID 27127173, 2016). "In this study, the effects of both AT and TQ on prostate cancer cell proliferation, anti-androgenic activity, and potential mechanism of AR protein down-regulation were evaluated." (PMID 26986969, 2016). "Despite the involvement of CSE/H2S system in AR signaling, their interactions in tumor development in both animal models and human prostate cancer patients remain to be elucidated." (PMID 27019751, 2016). "The majority of the diagnosed prostate cancers correspond to acinar adenocarcinomas that originate in the prostate gland and express the androgen receptor." (PMID 26682011, 2016). "Using non-destructive HR-MAS 1H NMR spectroscopy we analysed the metabolic changes induced by decreased AR signalling in human prostate cancer tissue samples." (PMID 27429605, 2016). "In prostate cancer, the expression intensity and pattern of the androgen receptor (AR) is used to predict the efficacy of anti-hormonal therapy." (PMID 27441183, 2016). "Enzalutamide is a potent inhibitor of AR signaling that is currently used as a first line therapy to treat prostate cancer patients with metastatic CRPC." (PMID 27409172, 2016). "Molecularly targeted therapies for advanced prostate cancer include castration modalities that suppress ligand-dependent transcriptional activity of the androgen receptor (AR)." (PMID 27897170, 2016). "In this study, we explored the regulatory mechanisms linking AR signaling with miR-1 expression in prostate cancer." (PMID 27991915, 2016). "It is now well established that the mediator of androgen action, the androgen receptor (AR), plays a key role in the progression of prostate cancer following ADT, despite castrate levels of circulating testosterone." (PMID 26907477, 2016). "The Androgen Receptor (AR) plays a key role in prostate biology and in the progression of prostate cancer (PCa) to castration resistance." (PMID 27683042, 2016).